GLYCAM1 (glycosylation dependent cell adhesion molecule 1 (pseudogene) )
Synonyms: GLYCAM1P
Gene: Long non-coding RNA gene on chromosome 12 (54,608,187 to 54,610,462, reverse strand). Ensembl gene ENSG00000293392.
Diseases named in the same sentence as GLYCAM1 in open-access papers:
GLYCAM1 is named in the same sentence as 7 diseases in open-access papers, as found by Europe PMC text mining. Sharing a sentence is not in itself a finding about the gene and the disease. The quoted sentences say what the papers report.
glaucoma (2 papers, 2017 to 2019). Increased pressure in the eyeball due to obstruction of the outflow of aqueous humor. "Supporting this, genetic knockout of Glycam1 on a DBA/2 J background increased glaucoma susceptibility (i.e. increased the risk that an eye would develop severe glaucoma) following radiation therapy." (PMID 30670050, 2019). "To investigate the role of Glycam1 in radiation-therapy in glaucoma, we developed the D2 mice with a null allele of Glycam1 (D2.Glycam1−/−)." (PMID 28446179, 2017). "Although genetic ablation of Glycam1 restored entry of monocyte-like cells into the ONH, glaucoma susceptibility was more modestly affected." (PMID 30670050, 2019). "Glycam1 is stably up-regulated following radiation treatment in glaucoma and monocyte entry into the optic nerve head is inhibited." (PMID 28446179, 2017). "As there is increased vascular permeability in human glaucoma patients, it is possible that secreted soluble GlyCAM1 arrives at the inner retina through vascular leakage." (PMID 28446179, 2017). "In conclusion, we discover that transcription and protein expression of the proteoglycan ligand GlyCAM1 is increased in the long term following radiation therapy in D2 glaucoma." (PMID 28446179, 2017). "The D2.Glycam1−/− mice and wild-type controls were γ-irradiated at 2–3 months of age and aged to the two key glaucoma time-points of 10.5 and 12 months of age." (PMID 28446179, 2017). "Another possibility is that the cells entering irradiated Glycam1 deficient eyes do not have the same properties as those entering wild-type D2 eyes and that they are less capable of inducing glaucoma." (PMID 28446179, 2017). "Glycam1 is constitutively up-regulated following radiation therapy and may protect from glaucoma by negatively modulating extravasation." (PMID 28446179, 2017). "Given the complexity of D2 glaucoma, as well as the complex, context-dependent regulation of extravasation, it is not surprising that Glycam1 does not solely mediate radiation-induced protection." (PMID 28446179, 2017). "Here, we generated a D2 substrain lacking Glycam1 to determine if GlyCAM1 is important for the radiation-induced neuroprotection and to determine if increased levels of GlyCAM1 impede extravasation in glaucoma." (PMID 28446179, 2017).
breast carcinoma (1 paper, 2015). "GLYCAM1 expression has not been evaluated in human breast cancer." (PMID 25633981, 2015).
colorectal cancer (1 paper, 2025). A primary or metastatic malignant neoplasm that affects the colon or rectum. "Notably, LncRNAs NEAT1, LOC152578, GLYCAM1, and SARS exhibited significantly reduced expression levels following aspirin treatment compared to untreated colorectal cancer cells." (PMID 40953835, 2025).
mastitis (1 paper, 2023). Inflammation of breast tissue during lactation or postpartum due to an obstructed duct or infection. "Although with no classification on PANTHER, the abundance of GLYCAM-1 significantly decreased during the course of lactation progression and in subclinical S. uberis mastitis milk compared to controls." (PMID 37889706, 2023).
tumor (5 papers, 2010 to 2024). "In keeping with the phenotypic loss of HEVs in tumor LNs, the expression levels of Glycam1, Chst4, Icam1, and Ccl21a were progressively reduced in HEC1 to HEC3, similar to the reduction of gene expression of PNAd producing glycan-generating enzymes." (PMID 34706240, 2021). "We found that, upon treatment with IM ± anti-VEGF, tumor endothelial cells expressed higher levels of Glycam1, which is expressed in mature HEVs." (PMID 36113478, 2022). "However, together with the lower expression levels of multiple glycosyl transferases, particularly Chst4, the overall lower level of Podxl, Glycam1, and Cd300lg in PNAd+ TEC may also contribute to the lower level of PNAd expression on the tumor vasculature." (PMID 36189308, 2022). "Thus, changes in Gast, Ccla3, Glycam1, Spp1, Serpina1a, Cela1, Cldn2, and Fabp2 are a result of GW501516 treatment and are not tumor specific." (PMID 21318167, 2010).
GLYCAM1 also shares sentences with these, for which no sentence is quoted: cancer (2 papers); Glucose intolerance (1).